HEXIM2 (HEXIM P-TEFb complex subunit 2)
Description:
Transcriptional regulator which functions as a general RNA polymerase II transcription inhibitor. Core component of the 7SK RNP complex: in cooperation with 7SK snRNA sequesters P-TEFb in a large inactive 7SK snRNP complex preventing RNA polymerase II phosphorylation and subsequent transcriptional elongation.
Synonyms: L3; FLJ32384
Tractability: PROTAC: ubiquitination databases record sites on it.
Gene: Protein-coding gene on chromosome 17 (45,160,700 to 45,170,701, forward strand). Ensembl gene ENSG00000168517.
Subcellular location: Nucleus
Subcellular location (Human Protein Atlas): Nuclear speckles; Nucleoplasm
Gene Ontology:
Molecular function: 7SK snRNA binding; cyclin-dependent protein serine/threonine kinase inhibitor activity; identical protein binding; protein binding; snRNA binding
Biological process: negative regulation of DNA-templated transcription; negative regulation of G2/M transition of mitotic cell cycle; negative regulation of transcription by RNA polymerase II
Cellular component: nuclear speck; nucleoplasm; nucleus; cytoplasm
Genetic constraint (gnomAD): Loss-of-function variants: 0 observed, 1.1 expected, observed/expected ratio (o/e) 0, 90% interval 0 to 1.69. That is too few expected variants to judge how well the gene tolerates losing a copy. Missense variants: 408 observed, 377.11 expected, observed/expected ratio (o/e) 1.08, 90% interval 1 to 1.17. Synonymous variants: 159 observed, 154.01 expected, observed/expected ratio (o/e) 1.03, 90% interval 0.91 to 1.18.
Homologues: Orthologues: chimpanzee HEXIM2 (100% identical), macaque HEXIM2 (98% identical), pig HEXIM2 (84% identical), dog HEXIM2 (83% identical), rabbit HEXIM2 (79% identical), mouse Hexim2 (77% identical), rat Hexim2 (76% identical), zebrafish hexim1 (39% identical), Drosophila melanogaster Hexim (24% identical). Paralogues in human: HEXIM1 (44% identical).
Diseases named in the same sentence as HEXIM2 in open-access papers:
HEXIM2 is named in the same sentence as 3 diseases in open-access papers, as found by Europe PMC text mining. Sharing a sentence is not in itself a finding about the gene and the disease. The quoted sentences say what the papers report.
insomnia (1 paper, 2025). A sleep disorder characterized by difficulty in falling asleep and/or remaining asleep. "For Sleeplessness/Insomnia, the top signal was a Bonferroni-significant association with the expression of SMAD5 in blood (eQTLGen; PSMR = 3.25 × 10−11), complemented by pQTL evidence linking it to HEXIM2 (deCODE; PSMR = 3.46 × 10−10)." (PMID 41296471, 2025).
latent infection (1 paper, 2023). "The expression of several factors implicated in the inhibition of viral transcription elongation, such as PCF11 (4.3-fold), GPS2 (2.6-fold), HEXIM1 (3.7-fold), and HEXIM2 (2.7-fold), was significantly upregulated in latent infection compared to actively infected cells." (PMID 38038477, 2023).
HEXIM2 also shares sentences with these, for which no sentence is quoted: glioma (1 paper).